MMUT (methylmalonyl-CoA mutase)
Description:
Catalyzes the reversible isomerization of methylmalonyl-CoA (MMCoA) (generated from branched-chain amino acid metabolism and degradation of dietary odd chain fatty acids and cholesterol) to succinyl-CoA (3-carboxypropionyl-CoA), a key intermediate of the tricarboxylic acid cycle.
Synonyms: MCM; MUT
Tractability: Small molecule: a structure with a bound ligand is known; it has a high-quality binding pocket. PROTAC: ubiquitination databases record sites on it.
Gene: Protein-coding gene on chromosome 6 (49,430,360 to 49,463,321, reverse strand). Ensembl gene ENSG00000146085.
Subcellular location: Mitochondrion matrix; Mitochondrion; Cytoplasm
Subcellular location (Human Protein Atlas): Cytosol; Mitochondria
Pathways (Reactome):
Disease: Defective MMAA causes MMA, cblA type; Defective MUT causes MMAM
Metabolism: Cobalamin (Cbl) metabolism; Propionyl-CoA catabolism
Gene Ontology:
Molecular function: cobalamin binding; GTPase activity; identical protein binding; methylmalonyl-CoA mutase activity; modified amino acid binding; protein binding; protein homodimerization activity; catalytic activity; intramolecular transferase activity; isomerase activity; metal ion binding
Biological process: homocysteine metabolic process; positive regulation of GTPase activity; succinyl-CoA biosynthetic process
Cellular component: cytoplasm; mitochondrial matrix; mitochondrion
Genetic constraint (gnomAD): Loss-of-function variants: 66 observed, 68.67 expected, observed/expected ratio (o/e) 0.96, 90% interval 0.79 to 1.18. The upper end of that interval is the gene's LOEUF score, 1.18, which puts it in group 5 of 6, group 1 being the genes least tolerant of losing a copy. Missense variants: 806 observed, 895.69 expected, observed/expected ratio (o/e) 0.9, 90% interval 0.85 to 0.95. Synonymous variants: 260 observed, 294.46 expected, observed/expected ratio (o/e) 0.88, 90% interval 0.8 to 0.98.
Gene-disease validity (ClinGen):
ClinGen rates the evidence that MMUT causes each of these diseases.
methylmalonic aciduria due to methylmalonyl-CoA mutase deficiency (autosomal recessive): Definitive. Vitamin B12-unresponsive methylmalonic acidemia is an inborn error of vitamin B12 (cobalamin) metabolism characterized by recurrent ketoacidotic crises or transient vomiting, dehydration, hypotonia and intellectual deficit, which does not respond to administration of vitamin B12.
Homologues: Orthologues: chimpanzee MMUT (99% identical), macaque MMUT (99% identical), rabbit MMUT (95% identical), dog MMUT (95% identical), rat Mmut (95% identical), mouse Mmut (95% identical), pig MMUT (95% identical), guinea pig MMUT (93% identical), zebrafish mmut (81% identical), Caenorhabditis elegans mmcm-1 (69% identical). Paralogues in human: MMAA (13% identical).
Diseases named in the same sentence as MMUT in open-access papers:
MMUT is named in the same sentence as 48 diseases in open-access papers, as found by Europe PMC text mining. Sharing a sentence is not in itself a finding about the gene and the disease. The quoted sentences say what the papers report.
methylmalonic acidemia (59 papers, 2007 to 2026). A genetically heterogenous inherited disorder characterized by abnormalities in the metabolism of lipids and proteins. "Methylmalonic acidemia is an autosomal recessive genetic disorder primarily caused by defects in methylmalonyl-CoA mutase and cobalamin (vitamin B12) metabolism." (PMID 42294815, 2026). "Background/Objectives: Isolated methylmalonic acidemia (iMMA) is a rare autosomal recessive metabolic disorder caused by defects in methylmalonyl-CoA mutase (MCM) activity or in the biosynthesis of its cofactor, adenosylcobalamin." (PMID 41828030, 2026). "Isolated methylmalonic acidemias (MMA) encompass a spectrum of organic acidemias caused by impaired activity of methylmalonyl-CoA mutase, which is encoded by the MUT gene and follows an autosomal recessive inheritance pattern." (PMID 40710547, 2025). "This study aims to describe the clinical picture of six patients with methylmalonic acidemia who are homozygous for the NM_000255.4:c.322C>T or p.(Arg108Cys) MMUT variant." (PMID 40243530, 2025). "Methylmalonic acidemia (MMAemia) is an inborn error of metabolism caused by defects in methylmalonyl-CoA mutase (MMUT) or cobalamin (Cbl) metabolism." (PMID 41299235, 2025). "In China, isolated methylmalonic acidemia accounts for typically 30% of all types, and the MMUT gene deficiency accounts for 93.5% of the isolated methylmalonic acidemia." (PMID 39075538, 2024). "Four mutation types of the MMACHC gene (e.g., c.609G > A (p.Trp203Ter), c.567dupT (p.Ile190fs)) and six mutation types of the MMUT gene (e.g., c.729_730insT (p.Asp244fs)) were found for methylmalonic acidemia." (PMID 39670100, 2024). "Isolated methylmalonic acidemia, an autosomal recessive disorder of propionate metabolism, is usually caused by mutations in the methylmalonyl-CoA mutase gene (mut-type)." (PMID 39075538, 2024). "For example, one group used methylmalonyl-CoA mutase (MUT)-expressing mRNA to treat methylmalonic acidemia caused by a deficiency in the MUT enzyme in mice." (PMID 35440755, 2022). "Propionic acidemia is caused by a deficiency of propionyl-CoA carboxylase and methylmalonic acidemia is caused by a deficiency of methylmalonyl-CoA mutase." (PMID 34295297, 2021). "Some hotspot mutations were observed for several IEMs, including PAH gene c.728G>A for phenylketonuria; MMACHC gene c.609G>A and c.567dupT, MMUT gene c.323G>A for methylmalonic acidemia and SLC25A13 gene c.852_855del for citrin deficiency." (PMID 33514801, 2021). "ImmTOR and AAV Anc80 encoding the methylmalonyl-coenzyme A (CoA) mutase (MMUT) combination was tested in a mouse model of methylmalonic acidemia, a disease caused by mutations in the MMUT gene." (PMID 34485611, 2021). "Methylmalonic acidemia (MMA) is an autosomal recessive inborn error of intermediary metabolism caused by the deficiency of methylmalonyl-CoA mutase (MMUT) — a mitochondrial enzyme that mediates the degradation of certain amino acids and lipids." (PMID 32548571, 2020). "Here the authors use cell and animal models to show that MMUT mutations lead to defective mitophagy and stress in kidney cells, contributing to the pathogenesis in methylmalonic acidemia patients." (PMID 32080200, 2020). "Methylmalonic acidemia (MMA) is a rare inborn error of metabolism caused by deficiency of the methylmalonyl-CoA mutase (MUT) enzyme." (PMID 32679819, 2020). "Methylmalonic acidemia is an inherited metabolic disease caused by loss or mutation of the enzyme MMUT." (PMID 32080200, 2020). "Deficiency of propionyl-CoA carboxylase causes propionic acidemia and deficiencies of methylmalonyl-CoA mutase or its cofactor adenosylcobalamin cause methylmalonic acidemia." (PMID 31451751, 2019). "Methylmalonic acidemia (MMA) is heterogenous inborn error of metabolism most typically caused by mutations in the vitamin-B12-dependent enzyme methylmalonyl- CoA – mutase (MUT)." (PMID 29322327, 2018).
methylmalonic acidemia (continued). "Methylmalonic acidemias (MMAs) are inborn errors of metabolism due to the deficient activity of methylmalonyl-CoA mutase (MUT)." (PMID 30428564, 2018). "Methylmalonic acidemia (MMAemia) is a rare hereditary disease caused by the accumulation of methylmalonic acid (MMA) due to metabolic disorders related to methylmalonyl-CoA mutase (MCM) or vitamin B12, the coenzyme of MCM." (PMID 32026114, 2018). "Methylmalonic acidemia is a neurometabolic disorders with autosomal recessive inheritance, which is caused by methylmalonyl-CoA mutase deficiency." (PMID 24665309, 2013). "Mutations in the methylmalonyl-CoA mutase (MUT) gene are the cause of mut class methylmalonic acidemia." (PMID 17937813, 2007). "Methylmalonic acidemia (MMA) caused by complete or partial deficiency of the mitochondrial enzyme methylmalonyl-CoA mutase (mut0 or mut- enzymatic subtype, respectively) leads to the accumulation of toxic organic acids, causing severe organ dysfunction and life-threatening complications." (PMID 41399536, 2025). "Isolated methylmalonic acidemia (MMA) is a rare group of inborn errors of metabolism caused either by a deficiency of the enzyme methylmalonyl‐CoA mutase (MMUT), defects in the transport or metabolism of its cofactor, adenosylcobalamin, or deficiency of the enzyme methylmalonyl‐CoA epimerase." (PMID 40365323, 2025). "Three cases were isolated methylmalonic acidemia, and carried six mutation types in the MMUT gene." (PMID 39670100, 2024). "Previous reports have indicated that metabolic disorders and respiratory failure are the most common causes of genetic death in the first two weeks after birth, and that methylmalonic acidemia caused by MMUT gene mutation is a major contributor to this outcome." (PMID 38750596, 2024). "Mutations in methylmalonyl-CoA mutase cause methylmalonic acidemia, a common organic aciduria." (PMID 17937813, 2007). "Methylmalonic acidemia is a bit more complicated because it can be caused by mutations in either methylmalonyl-CoA racemase, methylmalonyl-CoA mutase, or in enzymes involved in the processing of vitamin B12, which is an essential cofactor for methylmalonyl-CoA mutase." (PMID 32857789, 2020). "Propionic acidemia and methylmalonic acidemia are autosomal recessive inborn errors of metabolism resulting from dysfunctional propionyl-CoA carboxylase and methylmalonyl-CoA mutase, respectively." (PMID 40710547, 2025). "Fibroblasts from patients with methylmalonic acidemia due to a deficit of methylmalonyl-CoA mutase (MCM or MUT) activity were also reported to have CoQ10 contents below normal values." (PMID 38722242, 2024). "Methylmalonic acidemia (MMA) is a rare metabolic disorder resulting from functional defects in methylmalonyl-CoA mutase." (PMID 37248539, 2023). "Methylmalonic acidemia (MMA) is an autosomal recessive metabolic disorder that is mainly caused by inherited defects in methylmalonyl-CoA mutase (MCM, MUT) or metabolic defects in its cofactor adenosylcobalamin." (PMID 35919035, 2022). "Therapeutic trial of vitamin B12 (adenosylcobalamin), the cofactor for methylmalonyl-CoA mutase, can be considered in methylmalonic acidemia." (PMID 34295297, 2021). "Methylmalonic acidemia (MMA) is one of the most common inherited metabolic disorders, due to deficiency of the mitochondrial methylmalonyl-coenzyme A mutase (MMUT)." (PMID 32080200, 2020). "Methylmalonic acidemia (MMA) is an autosomal recessive disorder, characterized by an enzymatic defect in propiogenic amino acid metabolism due to methylmalonyl-CoA mutase (MUT) deficiency, limiting the conversion of methylmalonyl-CoA to succinyl-CoA." (PMID 32069872, 2020). "Methylmalonic acidemia (MMA), which is an autosomal recessive metabolic disorder, is caused by mutations in methylmalonyl-CoA mutase (MUT) gene." (PMID 32013889, 2020).
methylmalonic acidemia (continued). "Methylmalonic acidemia (MMA), the most common inborn disorder of organic acid metabolism, is inherited as an autosomal recessive disease caused by defects of methylmalonyl CoA mutase (MCM) or disorders of intracellular cobalamin metabolism." (PMID 26149271, 2015). "Methylmalonic acidemia (MMA), a common organic aciduria, is caused by deficiency of the mitochondrial localized, 5'deoxyadenosylcobalamin dependent enzyme, methylmalonyl-CoA mutase (MUT)." (PMID 17470278, 2007). "Isolated methylmalonic acidemia (MMA) is a rare, genetically heterogeneous group of metabolic disorders resulting from a deficiency of the enzyme methylmalonyl‐CoA mutase (MMUT), defects in the metabolism of its cofactor, adenosylcobalamin, or deficiency of the enzyme methylmalonyl‐CoA epimerase." (PMID 40365323, 2025). "Mutations in the MMUT gene can cause MUT deficiency, leading to methylmalonic acidemia (MMA)." (PMID 40243530, 2025). "However, lipodystrophy has been reported in methylmalonic acidemia patients who have a defect in methylmalonyl CoA mutase which converts intermediates of isoleucine and valine catabolism to succinyl-CoA." (PMID 39551140, 2024). "Methylmalonic acidemia (MMA, OMIM #251000) is a prototypic organic aciduria caused by impaired activity of the 5′deoxy-adenosylcobalamin–dependent (vitamin B12–dependent) mitochondrial enzyme methylmalonyl-CoA mutase (MMUT) (MMUT or MCM, EC 5.4.99.2)." (PMID 38271099, 2024). "For instance, one of the most common causes of congenital methylmalonic acidemia is a point mutation leading to inactivation of the mitochondrial enzyme methylmalonyl-CoA mutase (MMUT), which results in no response to treatment with B12." (PMID 38017447, 2023). "Methylmalonic acidemia (MMA), the most common form of organic acidemia, is the result of methylmalonyl COA mutase (MCM) enzyme deficiency or defect in synthesis or transport of its coenzyme, adenosylcobalamin (AdoCbl), or deficiency of methylmalonyl-CoA epimerase enzyme." (PMID 37430309, 2023). "Methylmalonic acidemia (MMA), a rare inborn error of metabolism caused by deficiency of the enzyme methylmalonyl-CoA mutase (MMUT), severely affects cell types/organs heavily reliant on energy demand, e.g., the brain, and eyes, kidney, liver, heart, and endocrine and skeletal systems." (PMID 36231140, 2022). "For methylmalonic acidemia, the diagnosis can be confirmed molecularly by identifying mutations in the MMUT gene that encodes the enzyme methylmalonyl-CoA mutase, and enzymatically by measuring the methylmalonyl-CoA mutase enzyme activity." (PMID 34295297, 2021). "Methylmalonic acidemia (MMA; McKusick 251000) is caused by methylmalonyl-CoA mutase deficiency." (PMID 24422943, 2014). "Methylmalonic acidemia (MMA), closely associated with PA, is an AR disease caused by deficiency of the methylmalonyl-CoA mutase enzyme, which can be dysfunctional due to several different genetic defects (gene MMUT or one of the genes of intracellular cobalamin pathway." (PMID 41425985, 2025). "Methylmalonic Acidemia (MMA) is a severe, sometimes lethal, monogenic inborn error of metabolism with onset during infancy caused by a mutation in the human methylmalonyl-CoA mutase (MMUT) gene resulting in high methylmalonic acid in all body fluids, causing metabolic crisis." (PMID 40143050, 2025). "Isolated methylmalonic acidemia encompasses a heterogeneous group of inborn errors of metabolism with a wide spectrum of phenotypic severity, rate of disease progression, and long-term outcomes, especially for patients with the severe MMUT or MMAB enzymatic defects." (PMID 33820958, 2021). "Methylmalonic acidemia (MMA) is the most common inborn error of organic acid metabolism, mainly due to methylmalonyl-CoA mutase (MCM) or its coenzyme cobalamin (vitamin B12) metabolic disorders with an autosomal recessively inherited form." (PMID 36704130, 2022).
methylmalonic acidemia (continued). "Methylmalonic acidemia cblB type (MMA cblB) is an autosomal recessive inborn error of amino acid metabolism that results in impaired synthesis of adenosylcobalamin, a cofactor of methylmalonyl-CoA mutase." (PMID 38444575, 2024). "Methylmalonic acidemia (MMA, MIM#251000) and propionic acidemia (PA, MIM#606054) are autosomal recessive organic acidemias that are characterized by the accumulation of methylmalonate or propionate due to a defect in either methylmalonyl-CoA mutase (MUT) or propionyl-CoA carboxylase (PCC)." (PMID 30940196, 2019).
Methylmalonic aciduria (19 papers, 2013 to 2025). Increased concentration of methylmalonic acid in the urine. "In humans, numerous pathogenic variants of the MMUT gene cause “methylmalonic aciduria” (OMIM 609058, MMA,), an autosomal recessive metabolism disorder." (PMID 38424485, 2024). "It has been shown in model mice with liver-specific MMUT knockout and patients with methylmalonic aciduria, a disease caused by mutations in genes encoding vitamin B12-interacting proteins." (PMID 38732262, 2024). "Methylmalonic aciduria (MMA-uria) is caused by deficiency of the mitochondrial enzyme methylmalonyl-CoA mutase (MUT)." (PMID 37169781, 2023). "Metabolism of cobalamin-associated A (MMAA) gene is essential for the proper functioning of a cofactor of the methylmalonyl-CoA mutase, whose mutation was associated with the clinical treatment effects of methylmalonic aciduria." (PMID 35847888, 2022). "Isolated methylmalonic aciduria can be caused by pathogenic mutations in the gene for methylmalonyl-CoA mutase or in the genes encoding enzymes involved in the intracellular metabolism of cobalamin." (PMID 34915869, 2021). "Patients with deficient activity of MMUT suffer from isolated methylmalonic aciduria (MMAuria), frequently presenting in the newborn period with failure to thrive and metabolic crisis." (PMID 33728246, 2021). "This is illustrated in the example of methylmalonyl CoA mutase (MUT), one of the two destination enzymes requiring the vitamin B12 cofactor for catalysis, where to date >130 missense mutations are found on this 750-amino acid polypeptide to cause methylmalonic aciduria (MIM 251000)." (PMID 27240455, 2016). "Deficiency in the MMUT, MMAA, and MMAB functions leads to a range of metabolic diseases named methylmalonic acidurias, which have an increased concentration of methylmalonic acid (MMA) in blood as a consequence." (PMID 38732262, 2024). "One of the causes of the disease is the methylmalonic aciduria, cblA type (cblA - type MMA), conditioned by a mutation in the MMAA gene, which is essential for the proper functioning of a cofactor of the methylmalonyl-CoA mutase." (PMID 31921599, 2020). "This point could be elucidated by the lack of response to B12 treatment in congenital methylmalonic aciduria resultant from MMUT gene mutations." (PMID 38017447, 2023).
organic acidemias (8 papers, 2019 to 2025). "Propionic (PA) and Methylmalonic (MMA) acidemia, the most frequent organic acidemias, are characterized by the accumulation of propionic and/or methylmalonic acid due to deficiency of propionyl-CoA carboxylase (PCC) or methylmalonyl-CoA mutase (MUT)." (PMID 40428324, 2025).
vitamin B12 deficiency (7 papers, 2016 to 2025). A disease characterized by low serum levels of vitamin B12, either inherited or acquired. "In the event of vitamin B12 deficiency, the activity of methylmalonyl-CoA mutase is hampered, resulting in a buildup of MMA within the body." (PMID 40635893, 2025). "Methylmalonic acid (MMA) is a metabolite that accumulates when the activity of cytosolic methylmalonyl-CoA mutase is decreased because of intracellular cobalamin deficiency." (PMID 36213409, 2022). "There is a second intriguing hypothesis that may be relevant: in cobalamin deficiency there is a failure to convert methylmalonic acid to succinic acid as cobalamin is a coenzyme in the enzyme methylmalonyl CoA-mutase." (PMID 34827292, 2021).
propionic acidemia (4 papers, 2018 to 2025). An organic aciduria caused by the deficient activity of the propionyl Coenzyme A carboxylase and is characterized by life threatening episodes of metabolic decompensation, neurological dysfunction and that may be complicated by cardiomyopathy. "The most common are Maple Syrup Urine Disease, Propionic Acidemia, and Methylmalonic Acidemia, which are caused by mutations in the methylmalonyl CoA mutase (MCM), propionyl‐CoA carboxylase (PCC), and branched‐chain α‐ketoacid dehydrogenase complex, respectively." (PMID 41244347, 2025).
lipodystrophy (2 papers, 2024). A congenital or acquired disorder characterized by abnormal loss or redistribution of the adipose tissue in the body. "Future studies should focus on exploring the functional impact of the two identified novel MMUT variants; investigating emerging phenotypic features, such as lipodystrophy, is also warranted." (PMID 39494389, 2024).